SQSTM1 (sequestosome 1)
Diseases named in the same sentence as SQSTM1 in open-access papers (continued):
Sharing a sentence is not in itself a finding about the gene and the disease.
dementia (10 papers, 2014 to 2024). Loss of intellectual abilities interfering with an individual's social and occupational functions. "Other proteins include dementia-associated proteins such as amyloid precursor protein (APP) and SQSTM1 protein, a protein associated with ubiquitination." (PMID 39696638, 2024). "The test of quantitative PCR showed significant decreased level of SQSTM1 mRNA from peripheral leucocytes of the patient compared to five dementia controls." (PMID 29467647, 2018). "No other pathogenic mutation in genes known to be associated with neurodegenerative diseases, and/or rare genetic causes of dementia, such as mutations in CHMP2B, FUS, TARDBP, SQSTM1 and VCP have been identified." (PMID 27632209, 2016). "SQSTM1 mutated patients displayed a classic phenotype without cognitive deficits at the time of diagnosis, with a family history for dementia in 28.6% of patients." (PMID 33770234, 2021). "For analyzing the gene transcription differences between the SQSTM1 S224X mutation and SQSTM1 wild type, we included another five dementia controls (female: 3, male: 2, and age matched) without the SQSTM1 mutation." (PMID 29467647, 2018). "Although the small sized of the samples adopted in the present study, it seemed that all dementia controls without SQSTM1 mutation presented an increased relative transcription level of SQSTM1 mRNA (up to 3.06 ± 0.88-fold) with regards to the patient (p < 0.05)." (PMID 29467647, 2018). "However, we have provided a clue for discussing the pathogenicity significance of SQSTM1 S224X mutation in FTD, which should foster an understanding of the effect of SQSTM1 mutation on FTD when the mutation can be verified in a large family showing dementia." (PMID 29467647, 2018). "Without a large family showing dementia and enough gene samples from family members, it is difficult to demonstrate that SQSTM1 S224X was fully responsible for FTD." (PMID 29467647, 2018). "Likewise we cannot exclude that some of the control individuals, who were selected based on absence of dementia-related symptoms, may have been at risk for/or suffered from PDB, in particular, those with the PDB-associated SQSTM1 p.P392L mutation." (PMID 24899140, 2014).
Sepsis (10 papers, 2017 to 2026). Sepsis is defined as life-threatening organ dysfunction caused by a dysregulated host response to infection. "We highlight the tissue-specific roles of SQSTM1 in sepsis-associated injury across major organs-including the liver, kidney, heart, lung, brain, and skeletal muscle-and explore its function as a damage-associated molecular pattern (DAMP) in the extracellular milieu." (PMID 41972740, 2026). "Moreover, MCOLN1-mediated lysosomal exocytosis exacerbates lipopolysaccharide (LPS)-induced secretion of SQSTM1, an autophagy receptor, which has been implicated in immune dysfunction and organ injury in sepsis patients." (PMID 40761792, 2025). "Moreover, the severity of sepsis in patients has been found to be associated with the activation of the SQSTM1–INSR pathway." (PMID 38020710, 2023). "In this review, we discuss the molecular mechanisms by which SQSTM1 regulates selective autophagy and immune signaling pathways, and how its dynamic modulation shapes host responses during sepsis." (PMID 41972740, 2026). "We conclude a stage- and compartment-specific model for SQSTM1 during sepsis: its transition from a protective intracellular autophagy mediator in the early stage to a pathological extracellular DAMP in late stage." (PMID 41972740, 2026). "In vitro and in vivo experiments have emphasized the role of extracellular SQSTM1 as a deadly inflammatory mediator leading to sepsis and septic shock mortality, according to recent research." (PMID 38020710, 2023). "Inversely, knocking down miR-130b-3p activated the AMPK/mTOR signaling pathway and upregulated the protein expression level of LC3A/B, and downregulated SQSTM1 in sepsis-induced cardiomyopathy mice." (PMID 37705752, 2023). "Lc3b and Bnip3 increased in the TA after 24, 48, and 96 h of sepsis, while Sqstm1 and Foxo1 increased after 24 and 48 h." (PMID 31660704, 2019). "Sepsis‐induced increases in Lc3b, Sqstm1, Bnip3, and Foxo1 mRNA levels were relatively higher in the TA than in the DIA." (PMID 31660704, 2019). "A better understanding of SQSTM1's dual roles in immune activation and resolution could open new avenues for precision therapies in sepsis." (PMID 41972740, 2026). "Blocking SQSTM1 by administering neutralizing monoclonal antibodies or deleting the INSR or SQSTM1 genes in bone marrow cells (BMCs) effectively safeguards mice from fatal sepsis." (PMID 38020710, 2023). "Functionally, the pathway involving SQSTM1 and INSR can have a significant impact on tissue damage, systemic inflammation, organ failure, and mortality in experimental sepsis mouse models when either genetically deleted or pharmaceutically inhibited." (PMID 38020710, 2023). "To characterize autophagy levels of CD4 + T cells in a mouse sepsis model, we assessed the expression of the autophagy proteins LC3II/I and p62/SQSTM1 in CLP mice and control mice." (PMID 35435531, 2022). "Lc3b and Sqstm1 increased in the DIA after 24 and 48 h of sepsis while Foxo1 only increased after 24 h." (PMID 31660704, 2019). "In the present study, we found that Erbin knockout impaired the autophagy process in both muramyl dipeptide (MDP)-induced bone marrow-derived macrophages (BMDMs) and sepsis mouse liver and lung, as detected by the accumulation of LC3-II and SQSTM1/p62, and autophagosomes." (PMID 38105228, 2023). "Additionally, we highlight important targets involved in sepsis‐related regulatory mechanisms, including GSDMD, HMGB1, STING, and SQSTM1, among others." (PMID 38020710, 2023). "In addition, we evaluated changes in expression of the autophagy protein LC3B and SQSTM1/p62 and found that both LC3-II conversion and the SQSTM1/p62 were increased in sALI patients compared to patients with sepsis but not ALI." (PMID 34218252, 2021).
colorectal cancer (9 papers, 2016 to 2025). A primary or metastatic malignant neoplasm that affects the colon or rectum. "In addition, HA1 increased the LC3B-II and SQSTM1 levels similar to those induced by CQ when each inhibitor was used at a concentration and time commonly used in colorectal cancer." (PMID 36831614, 2023). "To examine the potential of WWP2 to ubiquitinate NDP52, OPTN, and SQSTM1 in cells, we cotransfected Myc-tagged WWP2 and the corresponding FLAG-tagged autophagy receptors in the HCT116 colorectal cancer cell line." (PMID 35331737, 2022). "In Affymetrix primeview human GeneChip array, we found six upregulated genes (STAT1, ATF2, TNFRSF10B, TGFBR2, BAX, and SQSTM1) and two downregulated genes (SLC4A7 and CD274) related to apoptosis and proliferation of colorectal cancer cells after hsa_circ_0064559 knockdown." (PMID 37280630, 2023).
diabetes (9 papers, 2011 to 2025). "A recent paper in Nature Communications shows that pseudokinase TRIB3 has a critical role in the development of diabetes‐related cancers via interacting with SQSTM1, a selective autophagy receptor." (PMID 27038142, 2016). "In the present study, we found that mitochondrial morphological damages in the proximal tubular cells and p62/Sqstm1 accumulation in diabetic kidneys of WFRs occurred, which suggested that an impairment of autophagy system induced mitochondrial damage." (PMID 21949662, 2011). "In addition, mRNA expressions of inflammatory markers IL-1β and TNF-α were negatively correlated with protein levels of LC3B-II and positively correlated with SQSTM1 in PBMCs from type 2 diabetes mellitus patients." (PMID 36994103, 2023). "This study offers novel insights into the luteolin’s therapeutic potential in DR, particularly activating mitophagy through the SQSTM1/BNIP3L axis, which expands the scope of natural compounds in addressing this sight-threatening complication of diabetes." (PMID 40635752, 2025). "In patients with diabetes, YTHDC1 downregulation induces decreased SQSTM1 expression through accelerated SQSTM1 nuclear mRNA decay, leading to disturbed autophagic flux and keratinocyte migration, thus delaying wound healing." (PMID 38562618, 2024). "It was reported that the expressions of sequestosome 1 (SQSTM1)/p62, a receptor that regulates autophagy, and the m6A reader protein YTHDC1, were greatly decreased in both HG-treated human keratinocyte cells and in the epidermis derived from diabetic mice and patients with diabetes." (PMID 35692393, 2022).
leukemia (9 papers, 2016 to 2025). A malignant (clonal) hematologic disorder, involving hematopoietic stem cells and characterized by the presence of primitive or atypical myeloid or lymphoid cells in the bone marrow and the blood. "Then, the loss of SQSTM1 impairs leukemia progression in AML mouse models, underlying the role of mitophagy in the survival of LSCs." (PMID 37296673, 2023). "Silencing of p62/SQSTM1 decreased leukemia cell growth, which was associated with defective mitophagy, i. e., delayed removal of dysfunctional mitochondria and impaired mitochondrial respiration." (PMID 35526025, 2022). "Recent studies have also suggested that p62/SQSTM1 deficiency compromises cellular homeostasis in leukemia cells through the accumulation of dysfunctional mitochondria and impaired mitochondrial function." (PMID 33525345, 2021). "Although the role of mitophagy and mitochondrial homeostasis in cancer has been increasingly recognized, including the established function of SQSTM1 in leukemia progression, the specific mechanisms by which MRGs drive AML heterogeneity remain incompletely defined." (PMID 40873580, 2025). "SQSTM1 was recently shown to shuttle polyubiquitinated proteins to nuclear promyelocytic leukemia bodies, and a specific role in this context may warrant further examination." (PMID 27612428, 2016). "Moreover, SQSTM1-NUP214 caused myeloid leukemia in all transplanted mice, whereas none of the SQSTM1-NUP214FGmut reconstituted mice developed leukemia." (PMID 32343715, 2020).
osteosarcoma (9 papers, 2005 to 2025). A usually aggressive malignant bone-forming mesenchymal neoplasm, predominantly affecting adolescents and young adults. "In particular, the SQSTM1 (C1215T) mutation was reported at somatic level in samples from sporadic pagetic osteosarcoma patients, with the normal adjacent tissue from these tumors lacking this mutation, as expected for somatic mutational events." (PMID 36035996, 2022). "In addition, the study examined the association between the expression level of SQSTM1 and the clinicopathological characteristics of osteosarcoma." (PMID 39015499, 2024). "Interestingly, evidence of somatic SQSTM1 mutations in sporadic PDB and pagetic osteosarcoma suggested a role for SQSTM1 in both sporadic and inherited PDB and might in part explain the focal nature of the disorder." (PMID 36035996, 2022). "Then, we detected the expression of PRKCI and SQSTM1 in human osteosarcoma tissues and analyzed their correlation with the clinical characteristics of osteosarcoma, respectively." (PMID 39015499, 2024). "Relationship between SQSTM1 expression level and clinicopathological features in osteosarcoma (n = 20)." (PMID 39015499, 2024). "The expression of SQSTM1 in osteosarcoma tissues and adjacent tissues of 20 patients was detected by the IHC to further explore its role in human osteosarcoma." (PMID 39015499, 2024). "Rather both SQ1 and SQ2 caused the accumulation of autophagic cargo in two different cell types, in human osteosarcoma U2OS cells (in which SQSTM1 became more abundant) and in rat neuronal PC12 cells (in which a mutant Huntingtin Q74 construct accumulated)." (PMID 30858361, 2019). "Our current research elucidated the interaction between PRKCI and SQSTM1, demonstrating that PRKCI upregulated SQSTM1 and mediated critical functions in the proliferation and progression of osteosarcoma cells through the activation of the Akt/mTOR signaling pathway." (PMID 39015499, 2024). "Comparison of SQSTM1 protein expression in osteosarcoma cancer and cancer-adjacent tissues." (PMID 39015499, 2024). "The expression of PRKCI and SQSTM1 in osteosarcoma was higher than that in chondrosarcoma." (PMID 39015499, 2024). "Finally, the knowledge of the function of p62/SQSTM1 gene mutations should enable us to uncover the pathogenesis of PDB and osteogenic osteosarcoma." (PMID 16277682, 2005). "Overexpression of PRKCI enhanced the level of SQSTM1, p-mTOR, and p-AKT and inhibited the level of LC3B-II, indicating that overexpression of PRKCI could enhance the level of SQSTM1 and inhibit the level of autophagy through the Akt-mTOR pathway in osteosarcoma cells." (PMID 39015499, 2024). "Furthermore, we identified the interaction between PRKCI and SQSTM1 in osteosarcoma cell lines." (PMID 39015499, 2024). "However, the interaction between PRKCI and SQSTM1 in osteosarcoma remains unclear." (PMID 39015499, 2024). "The comparison between nontumor adjacent tissues and osteosarcoma strongly suggested a significant upregulation of SQSTM1 expression in the latter." (PMID 39015499, 2024). "SQSTM1, which interacted with PRKCI, was also overexpressed in osteosarcoma." (PMID 39015499, 2024). "In our investigation, we confirmed the abnormal expression of SQSTM1 in osteosarcoma tissues compared with nontumor tissues." (PMID 39015499, 2024). "Moreover, it has proteotoxic activity by inducing the formation of cytotoxic high molecular weight complexes, including the autophagosome component p62 (SQSTM1) and the transcription factor STAT3, a target of ROCK2, which was found downregulated in osteosarcoma upon verteporfin treatment." (PMID 32326412, 2020).
osteosarcoma (continued). "Simultaneously, the expression of SQSTM1 in tumor tissues was not related to clinical characteristics, and SQSTM1 interacted with PRKCI in U2OS cells, suggesting that SQSTM1 and PRKCI played a crucial role in osteosarcoma." (PMID 39015499, 2024).
proteinopathies (9 papers, 2016 to 2026). "SQSTM1 is mutated in ALS and loss of SQSTM1 function (by mutation or genetic KO) increases aggregative proteinopathies in various models of neurodegenerative disease, similar to loss of TAX1BP1." (PMID 41277110, 2026). "Herein, we report a new phenotype of SQSTM1-associated proteinopathy, a novel frameshift mutation in SQSTM1 causing proximal MRV." (PMID 36998782, 2023). "Illustratively, a SQSTM1 variant known to cause a multisystem proteinopathy through stress granule impairment was enhanced synergistically by a variant in TIA1, gene annotated to cause a distinct myopathy." (PMID 38239855, 2023). "SQSTM1 encodes for sequestosome 1, a protein required for the degradation of polyubiquitin-containing bodies that has been co-localized with intraneuronal ubiquitinated protein aggregates in individuals with protein misfolding diseases." (PMID 26807844, 2016). "Mutations in gene encoding sequestosome 1/p62 (SQSTM1) and valosin containing protein (VCP) also contribute to proteinopathies and immune dysregulation by impairing autophagy and the degradation of aggregated protein." (PMID 37307819, 2024). "Besides, colabeling experiments of ANXA11 with the SQSTM1 protein that aggregates in ANXA11 proteinopathies, showed colocalization in sarcoplasmic inclusions in muscle fibers thus supporting common mechanisms." (PMID 36651622, 2023). "In C9orf72-related ALS, TDP-43 proteinopathy is present, but additional inclusions devoid of TDP-43 are p62/sequestosome-1 and ubiquitin-positive." (PMID 32998318, 2020). "In addition, other studies have suggested that the co-localization between TDP-43, p62/SQSTM1 and ubiquitin is common in sporadic and familial ALS cases as well as in other TDP-43 proteinopathies." (PMID 28611593, 2017).
myeloma (8 papers, 2016 to 2024). "In multiple myeloma cells, a plastic SQSTM1/p62-dependent autophagic reserve has been implicated in maintaining proteostasis and determining PIs susceptibility." (PMID 37210387, 2023). "While under proteasome stress, SQSTM1/p62 de novo expression is selectively enhanced and its vast endogenous interactome are also reset in myeloma cells, thus promoting SQSTM1/p62 to divert from signaling partners to associate with ubiquitinated proteins." (PMID 30577555, 2018). "Taken together, these results suggest that myeloma cells can acquire tolerability to carfilzomib by increasing basal levels of SQSTM1." (PMID 27683126, 2016). "Also, the SQSTM1-KLF4-associated prosurvival autophagy contributes to CFZ resistance in MM models, while blocking SQSTM1 suppresses myeloma growth and osteoclast formation in vitro and induces bone formation in myeloma-bearing bones in vivo." (PMID 29707147, 2018). "SQSTM1 protein levels in myeloma cells could possibly represent a marker of carfilzomib sensitivity." (PMID 27683126, 2016). "Besides which, autophagic cargo receptor and adapter protein, SQSTM1/p62, is shown not only to synergize with the proteasome to maintain proteostasis, but also mediates a plastic adaptive response to proteasome inhibitors in multiple myeloma." (PMID 30577555, 2018). "Notably, our model also highlights high expression of the scaffolding protein SQSTM1/p62, a factor promoting RANK signalling but also conferring resistance to proteasome inhibitors in myeloma." (PMID 39198400, 2024).
non-small cell lung carcinoma (8 papers, 2014 to 2023). A group of at least three distinct histological types of lung cancer, including non-small cell squamous cell carcinoma, adenocarcinoma, and large cell carcinoma. "We found that CB-2 increased the LC3B-II and SQSTM1 levels associated with the accumulation of autophagosomes in non-small cell lung cancer (NSCLC) A549 cells." (PMID 34440609, 2021). "In this study we found that MV-Edm induced autophagy and sequestosome 1-mediated mitophagy leading to decreased cytochrome c release, which blocked the pro-apoptotic cascade in non-small cell lung cancer cells (NSCLCs)." (PMID 25004098, 2014). "Translocated promoter region (TPR) with NTRK1 was found in thyroid cancer, and sequestosome 1 (SQSTM1)-NTRK1 fusion in STS and non-small cell lung cancer (NSCLC)." (PMID 38144536, 2023). "For instance, Claudin1 has been shown to induce drug resistance mediated by autophagy in non-small cell lung cancer by ULK1 phosphorylation, and it acts as an autophagy stimulant, accelerating the degradation of SQSTM1/p62." (PMID 37303041, 2023).